RNU7-11P (RNA, U7 small nuclear 11 pseudogene)
Synonyms: U7.11
Gene: Small nuclear RNA gene on chromosome 4 (39,621,012 to 39,621,073, forward strand). Ensembl gene ENSG00000252796.
Homologues: Orthologues: macaque U7 (89% identical). Paralogues in human: RNU7-13P (94% identical), RNU7-25P (94% identical), RNU7-3P (94% identical), RNU7-6P (92% identical), RNU7-22P (90% identical), RNU7-2P (90% identical), RNU7-41P (90% identical), RNU7-47P (90% identical), RNU7-4P (90% identical), RNU7-7P (90% identical), RNU7-8P (90% identical), RNU7-1 (89% identical), and 143 more.